TMED9 (transmembrane p24 trafficking protein 9)
Diseases named in the same sentence as TMED9 in open-access papers (continued):
Sharing a sentence is not in itself a finding about the gene and the disease.
tumor (8 papers, 2007 to 2025). "Transcript differential analysis demonstrated that, compared to normal tissues, the protein transcripts encoded by TMED9 exhibit high expression in nearly all tumor types." (PMID 40124371, 2025). "Our eQTL-GWAS colocalization analysis identified specific single nucleotide polymorphisms (SNPs) of TMED9, such as rs6634 and rs34582406, which may share genetic variation across multiple tumor types, thereby providing novel genetic evidence for the tumor susceptibility associated with TMED9." (PMID 40124371, 2025). "Additionally, TMED9 was significantly associated with multiple tumor subtypes." (PMID 40124371, 2025). "Altogether, these findings point to the oncogenic role of TMED9 not only in the stem cell population, but also in the differentiated tumor cell progeny." (PMID 40497947, 2025). "The results demonstrated that in kidney renal clear cell carcinoma (KIRC), brain lower grade glioma (LGG), and liver hepatocellular carcinoma (LIHC), TMED9 expression progressively increased with tumor progression." (PMID 40124371, 2025). "Our findings reveal significant upregulation of TMED9 mRNA and protein levels across multiple tumor tissues, consistent with prior research." (PMID 40124371, 2025). "Correlation analysis further supported these localization findings, demonstrating a significant positive correlation between TMED9 expression levels and the abundance of tumor cells and macrophages in the sampled regions." (PMID 40124371, 2025). "In the differential analysis of tumor and normal samples from the TCGA, we found that TMED9 is significantly overexpressed in more than half of the tumor types." (PMID 40124371, 2025). "Immunological analysis indicates that TMED9 correlates positively with immune cell infiltration, particularly macrophages, suggesting its role in promoting tumor immunity." (PMID 40124371, 2025). "We also observed that TMED9 transcripts were more highly expressed in HCC tumor samples compared to normal liver tissues." (PMID 33888099, 2021). "TMED9 itself has been implicated in the WNT/β-catenin signaling pathway, as well as in affecting growth factor signaling, both are key drivers of tumor progression and therapy resistance." (PMID 40497947, 2025). "To gain insight into BRD4780′s mechanism of action, we first investigated whether the drug exerts its anti-tumor effects by altering TMED9 abundance." (PMID 40497947, 2025). "Furthermore, TMED9 expression was negatively correlated with tumor stemness, indicating its potential influence on chemotherapy resistance." (PMID 40124371, 2025). "In addition to TMED9 expression (hazard ratio (HR), 1.463; p = 0.047), the tumor size (HR, 1.543; p = 0.023), portal vein invasion (HR, 3.463; p < 0.001), and hepatic vein invasion (HR, 3.971; p < 0.001) were all shown to have adverse impacts on OS." (PMID 33888099, 2021). "Moreover, it keeps tumor growth local through repression of pro-metastatic TMED9-TGFα signaling via its downregulation of TMED9, CNIH4, TGFA, and GLI1." (PMID 31253868, 2019). "Consequently, TMED9 may facilitate tumor recognition and clearance by the immune system through enhanced antigen presentation." (PMID 40124371, 2025). "Among the 50 most notable DEGs related to ERS displayed in the heatmap, we observed that 26 ERS regulators were dramatically up-regulated in tumor samples, with PPP1CA, CDK5, and TMED9 showing fold changes of 1.25, 1.67, and 1.05, respectively." (PMID 38440732, 2024). "In addition, we also examined TMED9 levels in paired N/T tissues in the GSE76311 dataset and normal tissue versus tumor tissue in GSE102079 dataset." (PMID 33888099, 2021).
cancer (7 papers, 2019 to 2025). A tumor composed of atypical neoplastic, often pleomorphic cells that invade other tissues. "Correlation analysis indicated that the copy number variation of TMED9 was significantly positively associated with its mRNA expression in almost all cancer types." (PMID 40124371, 2025). "The KEGG enrichment analysis of highly expressed genes within the TMED9 high-expression group suggested that TMED9 is associated with various functions, particularly signaling molecules and their interactions, as well as immune and cancer-related pathways." (PMID 40124371, 2025). "In particular, TMED9 has been implicated in autophagy, lysosomal sorting, viral replication and cancer, which we will discuss in this Mini-Review." (PMID 36733337, 2022). "ROC curves indicated that TMED9 may serve as a diagnostic biomarker for specific cancers." (PMID 40124371, 2025). "In our study, we analyzed the expression pattern, diagnostic value, prognostic significance, copy number variations, and epigenetic changes of TMED9 in pan-cancer using multi-omics data." (PMID 40124371, 2025). "The TMED family, particularly TMED9, has garnered attention for its involvement in cancer progression; however, its comprehensive role across various cancer types remains poorly understood." (PMID 40124371, 2025). "Gene Set Enrichment Analysis (GSEA) results indicated that the TMED9 high-expression group is significantly enriched in immune-related pathways across cancers such as ACC, BLCA, GBM, LGG, and TGCT." (PMID 40124371, 2025). "GSCs are of great importance to cancer progression and resistance to treatment, yet the functional involvement of TMED9 in the GSC population remains undetermined." (PMID 40497947, 2025). "This is the first time, to the best of our knowledge, that TMED9 has been shown to mediate cancer stem cell tumorigenesis." (PMID 40497947, 2025). "In summary, our study provides new evidence supporting the potential of TMED9 as a cancer biomarker through a systematic analysis of its expression characteristics, genetic alterations, and biological functions in pan-cancer contexts." (PMID 40124371, 2025). "In pan-cancer analyses, the expression of TMED9 demonstrated an overall upward trend, transitioning from homozygous deletion to high copy number amplification." (PMID 40124371, 2025). "Subsequent differential analysis utilizing normal samples from the GTEx database also revealed significant upregulation of TMED9 expression across nearly all cancer types." (PMID 40124371, 2025). "Although TMED9’s role in specific cancer types has been investigated, there is a lack of a comprehensive perspective to evaluate the expression patterns and functions of TMED9 across different cancer types." (PMID 40124371, 2025). "Roles for TMED9 in the regulation of cancer cell growth, APP processing, and protein degradation underscore the importance of this cargo receptor in health and disease." (PMID 36733337, 2022). "Little is known about the TMED family in cancer and, specifically, nothing is known about the possible participation of TMED9 and TMED7 in metastases." (PMID 31253868, 2019). "Additionally, we found a significant positive correlation between TMED9 copy number variations and its mRNA expression levels across almost all cancer types." (PMID 40124371, 2025). "Through multi-omics data analysis, we elucidated the expression landscape of TMED9 in pan-cancer." (PMID 40124371, 2025). "Using paired normal and tumor tissue and immunohistochemical staining, Yi-Chieh reported that TMED9 may be used as a predictive biomarker and potential treatment target, which was similar to the other cancer-related genes in other cancer types." (PMID 40356904, 2025). "Given the growing body of studies linking various TMED proteins to multiple cancer types, we propose that targeting TMED9 could be broadened as a therapeutic strategy for other malignancies." (PMID 40497947, 2025).
cancer (continued). "This limitation restricts our understanding of the mechanisms underlying TMED9’s role in pan-cancer and underscores the necessity for macroscopic pan-cancer studies to characterize the expression profile, genomic alterations, clinical prognostic value, and immunological features of the TMED9 gene." (PMID 40124371, 2025). "Elevated TMED9 expression has been observed in multiple cancer types." (PMID 36733337, 2022). "TMED9 expression may regulate cancer cell proliferation through its effect on growth factor signaling." (PMID 36733337, 2022). "Notably, in CHOL and UVM, TMED9 methylation levels significantly correlated with prognosis, suggesting that methylation status may serve as an important biomarker for predicting cancer outcomes." (PMID 40124371, 2025). "Furthermore, TMED9 expression correlates with the development of multiple cancer types." (PMID 36733337, 2022). "Different types of copy number variations have also been noted in other cancer types, such as ACC, BLCA, LUSC, and TGCT, further underscoring TMED9’s diverse role in various tumors." (PMID 40124371, 2025). "Herein, we first evaluated the effect of TMED9 knockdown on TMED9- and TMED3-modulated signaling molecules which have been reported in other cancer types." (PMID 33888099, 2021). "Although the role of TMED9 in specific cancer types has been extensively studied, current research has predominantly focused on individual cancer types, lacking a comprehensive perspective needed to evaluate the expression patterns and functions of TMED9 across different cancer types." (PMID 40124371, 2025). "In GBM, we observed that both cancer cell antigen release (step 1) and immune cell trafficking to tumors (step 4)—including the recruitment of CD4 T cells, Th22 cells, monocytes, neutrophils, and eosinophils—were significantly upregulated in the high TMED9 expression group." (PMID 40124371, 2025).
TMED9 also shares sentences with these, for which no sentence is quoted: ovarian carcinoma (2 papers); amyotrophic lateral sclerosis (1); bacterial infection (1); Blindness (1); clear cell renal cell carcinoma (1); colon adenocarcinoma (1); endocervical adenocarcinoma (1); hereditary spastic paraplegia (1); kidney cancer (1); kidney disease (1); liver cirrhosis (1); lung adenocarcinoma (1); lung squamous cell carcinoma (1); mesothelioma (1); myeloma (1); neurodegenerative disease (1); neurological disease (1); oral cancer (1); pancreatic adenocarcinoma (1); retinitis pigmentosa (1); testicular germ cell tumor (1); toxic (1); uterine corpus endometrial carcinoma (1).